VIM (vimentin)
Diseases named in the same sentence as VIM in open-access papers (continued):
Sharing a sentence is not in itself a finding about the gene and the disease.
cancer (continued). "Consistently, Wi-A, and not 3βmWi-A, caused reduction in cytoskeleton proteins (Vimentin, N-Cadherin) and active protease (u-PA) that are essential for three key steps of cancer cell metastasis (EMT, increase in cell migration and invasion)." (PMID 31757995, 2019). "Vimentin, an indicator of epithelial–mesenchymal transition, is regulated by Rab7a in cancer cells." (PMID 29769411, 2019). "In addition, we stained for Vimentin (VIM), which is a marker for epithelial-mesenchymal transition in cancer cells, and cortactin." (PMID 31804471, 2019). "Some cancer cells appeared to directly attach to the vimentin-positive CAF-like cells." (PMID 30670761, 2019). "To investigate whether TAMs were involved in EMT of cancer cells to promote the invasion and metastasis of ESCCs, we analysed the expression of an epithelial marker (E-cadherin) and mesenchymal marker (vimentin) in ESCC samples." (PMID 31186031, 2019). "Moreover, cholesterol treatment inverted metformin-repressed expressions of several cancer-associated genes (e.g., Bcl-xL BCL2, Zeb1, vimentin, BMI1)." (PMID 30625181, 2019). "Furthermore, mesenchymal markers (i.e., Vimentin or N-Cadherin) decrease the polarity of cancer cells and accelerate migration and invasion." (PMID 31611551, 2019). "Furthermore, we showed that in the presence of CDH11-rich cancer-associated fibroblasts (CAFs), MCF7 and MDA-MB-231 MBC cell lines acquired enhanced metastatic phenotype with increased CDH11, β-catenin, vimentin, and fibronectin (FN) expression." (PMID 31248373, 2019). "In addition, histological staining of the cancer samples revealed that most of the PDGFRβ expressing cells were localized in the vimentin-positive periepithelial stroma." (PMID 31690270, 2019). "While it is unclear how vimentin promotes cancer cell stemness, one possible way may involve promoting Erk-mediated phosphorylation of slug for EMT initiation." (PMID 31126068, 2019). "Moreover, multiple GlcNAc-bearing polymers interact with cancer cells, fibroblasts, and skeletal muscle cells via cell-surface vimentin." (PMID 31814834, 2019). "Thus, EMT features (such as increased expression of vimentin or EMT core transcription factors and cell–cell contact remodeling) have been associated with poor clinical parameters in a variety of cancers including NSCLC." (PMID 31546725, 2019). "Epithelial mesenchymal transition (EMT), where epithelial derived tumors acquit mesenchymal stem cells’ properties, indicates the possibility of cancer metastasis, and the up-regulated expression of vimentin and N-cadherin (markers of mesenchymal cells) suggests malignant transformation." (PMID 31391034, 2019). "In addition to fibroblasts and cancer cells, vimentin is also expressed in leukocytes and endothelial cells." (PMID 30696956, 2019). "We previously discovered that TS expression is correlated with the EMT phenotype in the NCI-60 transcriptomic database by using a pan-cancer EMT gene ratio (Vimentin/E-Cadherin, VIM/CDH1), but the mechanistic involvement of the TS enzymatic activity on EMT/CSCs has never been shown." (PMID 30737477, 2019). "A strong positive correlation was also established between the expression CDH11 and metastasis-associated genes, β-catenin and vimentin in MCF7 and MDA-MB-231 cells in the presence of cancer-associated fibroblasts (CAFs), suggesting enhanced metastatic potential." (PMID 31248373, 2019). "Hypermethylation of VIM was thought to suppress vimentin expression but in most of cancer vimentin levels were overexpressed which appears paradoxical indicating VIM hypermethylation may involve in oncogenic trait." (PMID 31653136, 2019). "This is most notable for vimentin, which is upregulated in cancer cells that have undergone EMT." (PMID 31126068, 2019). "However, the factors controlling VIM expression and its exact role in cisplatin resistance in different cancer types are still not well understood." (PMID 31684899, 2019).
cancer (continued). "Indeed, it was shown that along with vimentin intermediate filaments, plectrin provide a scaffold for invadopodia formation, facilitating cancer cell invasion extravasation for metastasis." (PMID 31675377, 2019). "Since SNU449 is at a more advanced stage of the cancer, it acquired some mesenchymal characteristics, hence the decrease in the epithelial marker, E-cadherin, and the increase in the mesenchymal markers, N-cadherin and Vimentin." (PMID 31781476, 2019). "Vimentin is particularly important during development and in cancer during EMT and metastasis." (PMID 30505430, 2018). "We used the antibodies of anti-vimentin to detect the cancer cells in lung tissue of all groups." (PMID 29935539, 2018). "Furthermore, in such tumors, cancer cells were positive for vimentin, suggesting that those cancer cells underwent the EMT in vivo." (PMID 30537992, 2018). "Vimentin’s contribution to cell migration may also help to explain its role in the spread of cancer." (PMID 29513221, 2018). "As EMT plays crucial role in cancer migration and invasion process, we then detected the mRNA and protein levels of epithelial marker E-cadherin and that of the mesenchymal markers fibronectin, vimentin, and N-cadherin." (PMID 29358655, 2018). "Because it has been demonstrated that cancer cells undergo EMT, acquiring the ability to migrate and metastasize in several previous studies, we analyzed the expression of associated markers including E-cadherin, Vimentin, and Snail by WB." (PMID 30034624, 2018). "Therefore, the EMT process that is associated with the expression of E-cadherin, vimentin, ZEB1 and ZEB2 is generally used to indicate the ability of cancer cell metastasis and invasion." (PMID 29559853, 2018). "In previous reports, the downregulation of UBE2C could increase the expression of E-cadherin and decrease the expression of Slug, Twist, and Snail49–51, which are transcriptional drivers for vimentin in human cancer." (PMID 29904125, 2018). "Interestingly, they express both E Cadherin and Vimentin, two markers that are mutually exclusive, except for cancer cells." (PMID 29990377, 2018). "While we only analysed two indicative markers here (E-cadherin and vimentin) any shift to a mesenchymal phenotype caused by EMT would cause loss of E-Cadherin and may directly inhibit the CD8+ cytotoxic T cell control of cancer." (PMID 29416729, 2018). "Increased vimentin expression is frequently used as an EMT marker in cancer." (PMID 29551776, 2018). "We believe that NANOGP8/TWIST/ZEB/PRRX1 may be the upstream regulators of EMT, and vimentin/N-caderin/E-caderin may be the structural components to endow cancer cells the EMT properties." (PMID 29689047, 2018). "Furthermore, vimentin has been shown to be a pharmacologically relevant target of Simvastatin in cancer cells." (PMID 30248895, 2018). "Previous studies show that ERG regulates the expression of frizzled class receptor 4, E-cadherin, vimentin, ras homolog family member A, vascular endothelial growth factor receptor 2, and zinc finger E-box binding homeobox 1/2 during cancer metastasis and epithelial–mesenchymal transition process." (PMID 29773901, 2018). "Hence, EpCAM represents an excellent measure for the level of epithelial differentiation of carcinoma cells in head and neck tumors, whereas vimentin depicts a gradual mesenchymal switch." (PMID 30275505, 2018). "In general, carcinomas express CK, whereas mesenchymal tumours express vimentin." (PMID 29621151, 2018). "However, there are carcinomas that show loss of CK expression, carcinomas that frequently co-express vimentin and carcinomas that rarely express both CK and vimentin." (PMID 29621151, 2018).
cancer (continued). "This might explain why cancers with high vimentin expression level are most likely to be aggressive." (PMID 28616237, 2017). "Vimentin overexpression relates to invasiveness and aggressiveness of cancer." (PMID 28620205, 2017). "Based on our bioinformatics analysis of Annexin A1 associated proteins and the literature on the critical roles of Annexin A1, namely, S100A9 and Vimentin in cancer invasion and metastasis, Annexin A1/Vimentin/S100A9 was selected interaction interactions for further study." (PMID 28355254, 2017). "As clone P2B9 was less capable of forming spheres than parental OPCT-1, this clone appeared to possess a smaller cancer stem/progenitor cell population than the parental cell line from which they were derived, despite being enriched for vimentin-positive, EMT-derived cells." (PMID 28094783, 2017). "The EMT of cancer cells is characterized by a downregulation of epithelial markers such as E-cadherin, α-cadherin, and γ-cadherin and acquisition of a mesenchymal phenotype, accompanied by upregulation of periostin, vimentin, fibronectin and N-cadherin." (PMID 28977942, 2017). "This is coupled with the increased expression of transcriptional repressors Slug and Snail in primary human OECs, as well as increased Vimentin and MMPs expression which are all well-established to promote an invasive and metastatic phenotype in various cancers." (PMID 29250491, 2017). "Taken together, these data reveal a new mechanism by which intermediate filaments regulate contractile actomyosin bundles, and may explain why elevated vimentin expression levels correlate with increased migration and invasion of cancer cells." (PMID 28096473, 2017). "TNF-α could induce Twist1 expression and overexpression of Twist1 could promote further metastasis, which increased the expression of MMP-9, MMP-2, CD44v6 and vimentin in cancer cells." (PMID 28774312, 2017). "During the EMT process, the cancer cell phenotype typically changes from epithelial to mesenchymal, followed by upregulation of an epithelial marker (E-cadherin) and downregulation of mesenchymal markers (e.g., N-cadherin, vimentin)." (PMID 28095858, 2017). "Additionally, Vimentin has also been involved in cell cycle regulation and adhesion, which further validates its role in the development and progression of human cancers." (PMID 28912668, 2017). "Antibiotic salinomycin could kill breast CSCs preferentially and induced the differentiation of mesenchymal-like cancers in vivo, as assessed by increased E-cadherin expression and decreased vimentin expression." (PMID 28134289, 2017). "It is showed that Vimentin may correlated with cancer progression and prognosis at the invasive frontier in many kinds of cancers." (PMID 28355254, 2017). "The aim of this study was to investigate whether serum biomarkers reflecting MMP-mediated degradation of type I collagen (C1M), type IV collagen (C4M) and citrullinated vimentin (VICM) were predictive of cancer-specific mortality." (PMID 28881747, 2017). "Moreover, overexpressing miR-182 in mesenchymal cancer cells decreased the expression of Vimentin, while suppressing miR-182 in epithelial cancer cells reduced E-cadherin expression." (PMID 27894095, 2017). "Finally, MLN4924 activates the expression of E-cadherin and inhibits Vimentin via a yet-to-be identified mechanism to remain cancer cells in an epithelial phenotype to prevent EMT." (PMID 28717191, 2017). "Recently it has been reported in cancer cells and fibroblasts that vimentin depletion induced phosphorylation of the microtubule-associated GEF-H1, and thereby increased RhoA activity, myosin light chain phosphorylation, actin stress fiber assembly and cell contractility." (PMID 28912461, 2017). "Vimentin has been suggested to regulate intracellular mechanical homeostasis by maintaining cytoskeleton architecture and the balance of cell force generation in cancer cells undergoing EMT22." (PMID 29162839, 2017).
cancer (continued). "To investigate whether activation of CXCL12/CXCR4 axis promotes EMT, we performed the assays of RT-PCR and Western blot to determine the expressions of E-cadherin and vimentin in cancer cells." (PMID 28176874, 2017). "Our results on the interplay between vimentin IFs and stress fibers may also explain why elevated expression levels of vimentin correlate with increased invasion and metastasis potential of cancer cells." (PMID 28096473, 2017). "To elucidate the molecular basis whereby MSI-2 promotes the malignant behaviors of CC cells, we examined the mRNA expression of several metastasis-related genes (SNAIL, Vimentin and E-cadherin) and cancer stem cell marker CD44 in MSI-2 overexpression cells or knockdown cells." (PMID 29073938, 2017). "Interestingly, double immunofluorescence staining showed that B7-H4 is coexpression with EMT-related markers, including p-Smad2/3, Snail and Vimentin, in carcinoma cells." (PMID 29190910, 2017). "Remarkably, the co-inoculated CAF3 survived in large numbers in tumors together with carcinoma cells for periods of up to 29 weeks after injection, as determined by immunohistochemistry using an antibody specific for human vimentin and α-SMA, which MCF-7 cells fail to express." (PMID 28178651, 2017). "AE treatment significantly restored epithelial cell marker protein E-cadherin, inhibited the stromal cell marker protein vimentin, and suppressed EMT-associated transcription factors, including Twist, Snail, Slug, and HIF-1α, inhibiting EMT induction in cancer cells." (PMID 27391337, 2016). "Therefore, we propose that vimentin-knockdown enhanced drug resistance in A2780 cells is partially arisen from the acquired cancer stem cell properties." (PMID 27322682, 2016). "Altered/high expression of vimentin has been noticed in various types of cancer." (PMID 27190522, 2016). "VIM interacts with many proteins, and is both regulated by and can regulate genes that effect cancer progression and EMT, so it is likely that our hits induce VIM expression through different interacting proteins further explaining the diverse cellular phenotypes observed." (PMID 27876705, 2016). "Importantly, the expression of CD163 in cancer cells had a significant relationship with E-cadherin and vimentin." (PMID 26769084, 2016). "In vitro study in the past has shown that overexpression of vimentin in normal epithelial cells at the contact surface with transformed cells is essential for the cell competition involved in epithelial defense against cancer." (PMID 27258067, 2016). "This suggests that vimentin knockdown reprograms cells to acquire cancer stem cell phenotype." (PMID 27322682, 2016). "The binding of 86C to CSV may then trigger rapid internalization of an 86C-vimentin complex by the cancer cells." (PMID 27713131, 2016). "Interestingly, the knock-down of Jagged1 and DLL4 also blocked Notch-induced invasion and migration along with increased E-cadherin and decreased N-cadherin and vimentin protein levels in irradiated MCF7 cancer cells." (PMID 27462787, 2016). "Remarkably, VIM is an important target gene for various cancers." (PMID 27034707, 2016). "Both HDAC5 and HDAC6 could influence the metastasis of A375 cells by regulating MMP9 and vimentin, both markers for the metastasis ability of cancer cells." (PMID 26747087, 2016). "A small fraction of intracellular vimentin may be released, externalized, and displayed on the surfaces of cancer cells by unconventional secretion." (PMID 27713131, 2016). "If EMT markers such as E-cadherin, N-cadherin, and vimentin are target genes of TTP in cancer cells, TTP might decrease the stability of the mRNA of these genes." (PMID 26840564, 2016). "Some anti-cancer drugs that are currently used in the clinic directly target vimentin." (PMID 26160837, 2015). "RT-PCR analysis of Vimentin and cancer stem cell surface markers." (PMID 26571380, 2015). "FSP-1 and VIM were also expressed in cancer cells, consistent with previous reports." (PMID 25973543, 2015).
cancer (continued). "A close relation between Vimentin and cancer cell migration capabilities has also been found." (PMID 25889491, 2015). "The much lower number of this type of cells in blood samples from healthy donors than the cancer patents indicates that at least a proportion of those CK-negative/Vimentin-positive/CD45-negative cells harvested by Parsortix may be mesenchymal CTCs." (PMID 26397728, 2015). "We hypothesized that vimentin mediated the reorganization of cytoskeletons to maintain the mechanical integrity in EMT cancer cells." (PMID 25965826, 2015). "Compared to diploid cancer cells, PGCCs with budding daughter cells and PGCCs alone express lower levels of cytokeratin and higher levels of vimentin, indicating that PGCCs and their budding daughter cells have undergone epithelial-mesenchymal transition (EMT)." (PMID 26702618, 2015). "On the other hand, human cancer cells grafted to nu/nu mice form tumors with stroma containing exclusively fibroblasts of the mouse origin, as was demonstrated by use of human-specific anti-vimentin antibodies." (PMID 26473842, 2015). "In addition, FAM84B gene expression is suppressed in cell line transfected with HIPK2 expression vector, which inhibits cancer cell invasion by down-regulating vimentin expression." (PMID 25980316, 2015). "A proportion of podoplanin-positive cancer cells also expressed vimentin, suggesting that podoplanin may result in vimentin-associated EMT." (PMID 26095281, 2015). "In particular, this study demonstrated that vimentin plays a crucial role in maintaining cytoskeleton architecture and cellular mechanical strength, as well as mediates the organization of microtubule polarity and induces cancer cell malignancy." (PMID 25965826, 2015). "Although detection of cell-surface vimentin in cancer cells has been demonstrated in different studies, its role as a biomarker by using a monoclonal antibody 84-1 for detecting CTC from blood of cancer patients affected by carcinoma as well as sarcoma has been established." (PMID 26167450, 2015). "Therefore, in EMT cancer cells, vimentin maintained cell mechanical integrity by serving as a coordinator among cytoskeletons to further arrange the delicate cytoskeleton architecture and maintain the mechanical strength of cells." (PMID 25965826, 2015). "Previous studies have shown that vimentin was upregulated in several types of cancer with poor prognoses, which is highly correlated with the upregulation of the EMT-related transcription factor, slug, and the downregulation of the adherent protein, E-cadherin." (PMID 25965826, 2015). "Furthermore, 10%-25% of B7H1+ cancer cells expressed vimentin, a mesenchymal marker, indicating EMT phenotype exist in certain B7H1+ cells." (PMID 26284927, 2015). "SPP1 overexpression in cancer cells led to the down-regulation of E-Cadherin and up-regulation of N-Cadherin and Slug at both the mRNA and protein levels, and up-regulation of Vimentin and Snail at the mRNA level." (PMID 26565418, 2015). "Following chromobody fluorescence in a cancer-relevant cellular model, we were able for the first time to monitor and quantify dynamic changes of endogenous vimentin upon siRNA-mediated knockdown, induction with TGF-β and modification with Withaferin A by high-content imaging." (PMID 26292717, 2015). "Vimentin overexpression in cancers and its correlation with growth and metastasis suggest that it might be an indicator of poor prognostic for many cancers." (PMID 26425122, 2015). "Because vimentin overexpression is generally recognized as a metastatic phenotype indicator in cancer cells, we hypothesized that ANX1 overexpression may serve a similar functional role in promoting metastasis in HCC cells." (PMID 26431426, 2015). "Then, we investigated whether the variation of migratory potential of TC-1 cells was associated with altered phenotype and induction of two EMT makers, Vimentin and Snail, in carcinoma cells." (PMID 25635683, 2015).